HOXC10 (homeobox C10)
Description:
Sequence-specific transcription factor which is part of a developmental regulatory system that provides cells with specific positional identities on the anterior-posterior axis.
Synonyms: HOX3I
Tractability: PROTAC: UniProt records ubiquitination sites on it; ubiquitination databases record sites on it.
Gene: Protein-coding gene on chromosome 12 (53,985,065 to 53,990,279, forward strand). Ensembl gene ENSG00000180818.
Subcellular location: Nucleus
Subcellular location (Human Protein Atlas): Nuclear bodies; Nucleoplasm
Gene Ontology:
Molecular function: DNA-binding transcription activator activity, RNA polymerase II-specific; protein binding; RNA polymerase II transcription regulatory region sequence-specific DNA binding; sequence-specific double-stranded DNA binding; DNA-binding transcription factor activity, RNA polymerase II-specific; RNA polymerase II cis-regulatory region sequence-specific DNA binding; DNA binding
Biological process: negative regulation of cold-induced thermogenesis; positive regulation of transcription by RNA polymerase II; positive regulation of cell population proliferation; regulation of transcription by RNA polymerase II; regulation of DNA-templated transcription
Cellular component: nuclear body; nucleoplasm; chromatin; nucleus
Genetic constraint (gnomAD): Loss-of-function variants: 15 observed, 26.5 expected, observed/expected ratio (o/e) 0.57, 90% interval 0.38 to 0.87. The upper end of that interval is the gene's LOEUF score, 0.87, which puts it in group 3 of 6, group 1 being the genes least tolerant of losing a copy. Missense variants: 446 observed, 477.92 expected, observed/expected ratio (o/e) 0.93, 90% interval 0.86 to 1.01. Synonymous variants: 196 observed, 200.15 expected, observed/expected ratio (o/e) 0.98, 90% interval 0.87 to 1.1.
Homologues: Orthologues: chimpanzee HOXC10 (99% identical), macaque HOXC10 (98% identical), guinea pig HOXC10 (98% identical), mouse Hoxc10 (97% identical), pig HOXC10 (97% identical), rat Hoxc10 (97% identical), dog HOXC10 (94% identical), rabbit HOXC10 (83% identical), tropical clawed frog hoxc10 (69% identical), zebrafish hoxc10a (42% identical). Paralogues in human: HOXD10 (44% identical), HOXA10 (42% identical), HOXC9 (25% identical), HOXB9 (23% identical), HOXD9 (23% identical), HOXC12 (21% identical), HOXB5 (19% identical), HOXA5 (18% identical), HOXD12 (18% identical), HOXC8 (18% identical), HOXA3 (18% identical), HOXD8 (18% identical), and 30 more.
Diseases named in the same sentence as HOXC10 in open-access papers:
HOXC10 is named in the same sentence as 42 diseases in open-access papers, as found by Europe PMC text mining. Sharing a sentence is not in itself a finding about the gene and the disease. The quoted sentences say what the papers report.
glioma (16 papers, 2017 to 2024). A benign or malignant brain and spinal cord tumor that arises from glial cells (astrocytes, oligodendrocytes, ependymal cells). "Up-regulation of HOXC10 promoted an aggressive phenotype in glioma and induced the expression of genes involved in tumor immunosuppression." (PMID 37334354, 2023). "On the contrary, HOXC10 was positively associated with IL6/JAK/STAT3 and IL2/STAT5 signaling in glioma, and previous studies also indicated that these two signaling pathways were activated." (PMID 38154103, 2023). "Many HOMEOBOX (HOX)-related genes (HOXD11, HOXD9, HOXC10, HOXC11, HOXC6, HOXB3, HOXA2, HOXA1) were associated with a glioma grade and significantly overexpressed in GIV (Wilcoxon rank-sum and BH padj < 0.05)." (PMID 36850002, 2023). "The growth of new capillaries in tumor tissue contributes to poor progression and metastasis, and it has been reported that HOXC10 is highly expressed in glioma and promotes angiogenesis." (PMID 38154103, 2023). "The T cell depletion-related prognostic model was developed based on seven prognostic genes (HSPB1, HOXD10, HOXA5, SEC61G, H19, ANXA2P2, HOXC10) in glioma." (PMID 36531217, 2022). "Another transcription factor proposed as a target in glioma treatment was HOXC10 (Homeobox protein Hox-C10)." (PMID 33498521, 2021). "Overexpression of HOXC10 has been reported to be able to enhance the ability of glioma cells to induce tube formation, migration, and proliferation of ECs, whereas silencing HOXC10 exerts the opposite effect." (PMID 33171691, 2020). "Except for HOXC10, which was down-regulated in one of the canine glioma cases, all other genes were overexpressed in all canine glioma cases." (PMID 31475119, 2019). "A series of studies have explored the function of HOXC10 in gliomas." (PMID 37334354, 2023). "Similarly, HOXC10 overexpression promotes angiogenesis in human gliomas through interaction with PRMT5 and upregulation of VEGFA expression in vitro." (PMID 36531217, 2022). "HOXC10 overexpression also inhibited the efficacy of radiotherapy in gliomas." (PMID 34113572, 2021). "Interestingly, PRMT5 was required for the overexpression of VEGFA mediated by HOXC10 representing a potential target for anti-VEGF therapy in glioma therapeutics." (PMID 33440687, 2021). "Thus, we speculated that HOXC10 might help glioma cells escape immune surveillance by regulating the expression of immunosuppressive genes, leading to cancer occurrence and development." (PMID 34113572, 2021). "Other mitochondrial genes such as ABCC3, HOXA4, HOXC10, NNMT, and SCNN1B are typically increased in their expression as the grade of glioma and the higher expression of these genes have been associated with poor prognosis in LGG." (PMID 39012280, 2024). "Hsa-miR-129-5p, a tumor suppressor, is down-regulated in gliomas and inhibits glioma proliferation, migration and development by targeting TGIF2, WNT5A, DNMT3A, HOXC10, FNDC3B." (PMID 35601497, 2022). "Overexpressed HOXC10 can interact with PRMT5 to promote the expression of VEGF, thereby promoting angiogenesis in gliomas and increasing the metastasis and invasion abilities of gliomas." (PMID 35201457, 2021). "Additionally, HOXC10 up-regulated the expression of VEGFA, enhancing the capacity of glioma angiogenesis, which made it a potential therapeutic target for antiangiogenic therapy." (PMID 37334354, 2023). "Previous studies have demonstrated the function of ABCC3, HOXA4, HOXC10, and NNMT in gliomas." (PMID 37334354, 2023). "A 20-gene signature was identified, which was associated with radiotherapy.Furthermore, a novel 5-gene signature (HOXC10, LOC101928747, CYB561D2, RPL36A and RPS4XP2) as an independent predictor of glioma patients’ prognosis was further derived from the 20-gene signature." (PMID 29179492, 2017). "Moreover, HOXC10 induces angiogenesis by upregulating the expression of VEGFA, and may be a potential antiangiogenic target for glioma." (PMID 38154103, 2023).
glioma (continued). "Additionally, HOXC10 and SIM2 demonstrated significant overexpression in human GBM (p ≤ 0.0001) and human ODG (p ≤ 0.04), respectively, but not in the other human glioma subtypes." (PMID 31475119, 2019).
breast carcinoma (13 papers, 2014 to 2025). "In addition, HOXC10 upregulation is associated with lymph node metastases and chemotherapy resistance in breast cancer 12, increased invasiveness in cervical squamous cell carcinomas and short survival in human lung adenocarcinoma 11,21." (PMID 31528218, 2019). "Previous studies have confirmed that HOXC10 participates in the development and progression of breast cancer and affects the prognosis of breast cancer patients." (PMID 37521466, 2023). "The overexpression of HOXC10 in breast cancer is related to drug resistance to chemotherapy and a positive correlation between immune cell infiltration and poor prognosis in BRCAs." (PMID 37521466, 2023). "Abnormal HOXC10 expression has been identified in other tumors, such as cervical cancer, breast cancer, non-small cell lung cancer, oral squamous cell carcinomas." (PMID 34113572, 2021). "In particular, HOXC10 has been reported to promote progression of various types of cancer, such as breast cancer." (PMID 32687064, 2020). "In breast cancer, elevated HOXC10 expression helped malignant cells to survive under serum-depleted or hypoxic conditions." (PMID 31528218, 2019). "HOXC10 dys-function is found in thyroid cancer, breast cancer and cervical squamous cell carcinomas." (PMID 29179492, 2017). "In breast cancer cells, estrogen can promote Hox transcription through its receptor α (estrogen receptor, ERα) and receptor β (estrogen receptor, ERβ) binding to estrogen response elements (EREs) in the HOXC10 promoter, thereby promoting tumor growth." (PMID 39706274, 2025). "In breast cancer, HOXC10 overexpression has been widely reported." (PMID 34113572, 2021). "Additionally, a study demonstrated that cases with high HOXC10 expression showed shorter recurrence-free and overall survival in patients with breast cancer undergoing chemotherapy." (PMID 34712617, 2021). "In breast cancer, oestrogen has been proposed to suppress HOXC10 expression." (PMID 32897245, 2020). "HOXC10 plays important roles in many types of cancer, and its upregulation is also found in human gastric cancer 18, cervical squamous cell carcinomas 19, and breast cancer." (PMID 31528218, 2019). "A recent report found that extended use of aromatase inhibitors resulted in the recruitment of EZH2 and hence increased H3K27me3 of the homeobox gene HOXC10 in breast cancer cells, ultimately leading to HOXC10 methylation and silencing and resistance to aromatase inhibitors." (PMID 25949794, 2014). "Moreover, other researchers have proposed that suppressing the function of HOXC10 might be a promising new strategy to overcome chemotherapeutic resistance in breast cancer." (PMID 32897245, 2020). "In total, seven TFs (HOXC11, FOXA1, SPDEF, SOX12, HOXC10, GATA3 and TFAP2A) were annotated to the breast cancer samples." (PMID 34712617, 2021). "HOXC10 is a member of the HOXC cluster and contributes to the development of several types of cancers, including glioma, breast cancer, osteosarcoma, and thyroid cancer." (PMID 32687064, 2020). "Four genes from breast cancer stage III network pattern (KRT8, KRT17, KRT18 and HOXC10) physically interact with EGFR, a target gene of Lapatinib Breast cancer drug which is quite similar (greater than 50%) to Paroxetine (repurposed drug from LINCS)." (PMID 26892392, 2016). "This suggested that HOXC10, FXYD1, MT1X, and IGF2 may play an important role in the development of luminal A breast cancer under the regulation of HOXC-AS3, AC020907.2, AC026461.1, and AC132217.1." (PMID 35692369, 2022).
gastric cancer (12 papers, 2018 to 2024). A primary or metastatic malignant neoplasm involving the stomach. "used tissue microarrays to test 73 gastric cancer patients and found that the HOXC10 expression level was strongly associated with tumor node metastasis (TNM) stage, lymph node metastasis, and distant metastasis." (PMID 34113572, 2021). "This is consistent with Kim’s study that suggested hypomethylation of HOXC10 CpG sites was associated with overexpression of HOXC10 in gastric cancer." (PMID 32687064, 2020). "However, there are also HOXC genes that are hypomethylated in cancer; this is the case of HOXC10 in gastric cancer, which is associated with cell proliferation and migration." (PMID 32635388, 2020). "A study also indicated that HOXC10 positively regulated the proliferation, migration, and invasiveness of gastric cancer by elevating proinflammatory factor expression through NF-κB signaling." (PMID 37876483, 2023). "HOXC10 is reported to accelerate the proliferative capacity and metastasis in gastric cancer by activating the MAPK signaling pathway." (PMID 37876483, 2023). "Accumulating evidence demonstrated the crucial role of HOXC10 in the development and progression of colorectal and gastric cancers." (PMID 36447287, 2022). "Bisulfite sequencing revealed that CpG sites in the first HOXC10 intronic region were hypomethylated in three gastric cancer tissues, and HOXC10 expression was increased in gastric cancer cell lines (AGS and SNU620) in response to 5-azacytidine treatment." (PMID 34113572, 2021). "used surgical specimens from gastric cancer patients with metastases and found that HOXC10 was the highest expressed gene in carcinoma compared with adjacent tissue." (PMID 34113572, 2021). "Miwaet al. used surgical specimens from gastric cancer patients with metastasis and found that HOXC10 was the highest expressed gene in the carcinoma tissues compared with adjacent tissues." (PMID 34113572, 2021). "In gastric cancer, up-regulation of HOXC10 promotes the proliferation and metastasis of gastric cancer cells by regulating NF-κB or MAPK pathway." (PMID 35201457, 2021). "In other studies, HOXC10 overexpression facilitated G1/S cell cycle transition by regulating the expression of cyclin D1 in gastric cancer cells." (PMID 34113572, 2021). "used the TCGA data to compare the gene expressions in gastric cancer and normal tissues and found that HOXC10 expression was significantly promoted in gastric cancer." (PMID 34113572, 2021). "HOXC10 is a target of miR-129-5p, and miR-129-5p inhibits gastric cancer development by regulating HOXC10/Cyclin D1 axis." (PMID 35201457, 2021). "injected gastric cancer cells overexpressing HOXC10 into the intragastric walls of mice to obtain gastric cancer tumor-bearing mice and confirmed that HOXC10 overexpression increased the gastric cancer tumor volum in these mice." (PMID 34113572, 2021). "HOXC10 is highly expressed in the poorly differentiated gastric carcinoma cells, and it accelerates proinflammatory cytokines through NF-κB signaling pathway to promote the progression of gastric carcinoma." (PMID 35201457, 2021). "Meanwhile, HOXC10 promotes gastric cancer cell invasion and migration via regulation of the Nuclear factor-κB (NF-κB) pathway." (PMID 31528218, 2019). "We also revealed the strong relationships between HOXC10 and gastric cancer cell proliferation and metastasis, which occur through the MAPK pathway." (PMID 30128179, 2018). "This suggests that HOXC10 promotes metastasis in peritoneal metastases of gastric cancer." (PMID 37876483, 2023). "HOXC10 is a direct target of miR-136, which prevents the peritoneal spread of gastric cancer." (PMID 37876483, 2023).
gastric cancer (continued). "Furthermore, HOXC10 was reportedly highly expressed in many human cancers, such as gastric cancer, lung cancer, multiple myelomas, oral squamous cell carcinoma, and HCC." (PMID 37733108, 2023). "In gastric cancer, HOXC10 was found to be a direct target of MiR-136." (PMID 36447287, 2022). "HOXC10 was also found to be involved in chemotherapy resistance in gastric cancer." (PMID 34113572, 2021). "In gastric cancer cell lines, increasing HOXC10 expression significantly promoted cell proliferation and metastasis, and gastric cancer cells proliferation and invasion were inhibited via increased apoptosis after HOXC10 gene silencing." (PMID 34113572, 2021). "For example, HOXC10 has a oncogenic effect in gastric cancer." (PMID 35201457, 2021). "Moreover, situations occur in which HOX genes are found to be hypomethylated during tumorigenesis; this is the case of HOXC10 in gastric cancer." (PMID 32635388, 2020). "Thus, HOXC10 induces gastric cancer cell invasion and migration through the ATM/NF-κB axis." (PMID 34113572, 2021). "Mechanistically, HOXC10 could activates the NF-κB pathway by binding to the p65 gene promotor and indirectly upregulating inflammatory cytokines (IL-6, TNF-α, TGF-β, EGF) in gastric cancer cells." (PMID 34113572, 2021).
colorectal cancer (6 papers, 2021 to 2025). A primary or metastatic malignant neoplasm that affects the colon or rectum. "Upregulation of HOXC10 is closely associated with colorectal cancer progression." (PMID 35201457, 2021). "SB225002 has been reported to significantly inhibit the HOXC10-mediated colorectal cancer metastasis in combination with anti-PD-L1 therapy." (PMID 41155662, 2025). "Colorectal cancer derived exosomal miR-146b-5p acting through Homeobox C10 (HOXC10) has also been shown to elicit adipose tissue browning." (PMID 36672227, 2023). "Additionally, another study demonstrated that HOXC10 overexpression activated MTFR2 expression, thereby enhancing the proliferation, clone formation, invasion, and migration of colorectal cancer cells." (PMID 40129972, 2024).
oral squamous cell carcinoma (6 papers, 2019 to 2024). "Wnt10B overexpression promoted migration ability in oral squamous cell carcinoma cells, but this process was reversed after HOXC10 silencing." (PMID 34113572, 2021). "Therefore, we concentrate on elucidating the role of HOXC10 in progression of oral squamous cell carcinoma (OSCC)." (PMID 31528218, 2019).
lung adenocarcinoma (5 papers, 2019 to 2024). A carcinoma that arises from the lung and is characterized by the presence of malignant glandular epithelial cells. "Elevated expression of HOXC10 was associated with poor overall and disease-free survival in the TCGA Lung Adenocarcinoma cohort." (PMID 32687064, 2020). "We further explored the association between HOXC10 expression and the survival outcomes of patients in KRAS-mutant lung adenocarcinoma (LUAD) subgroups using TCGA datasets." (PMID 39191757, 2024). "Results from our clinical samples indicated that HOXC10 was an independent predictor for distant metastasis-free survival in lung adenocarcinoma (LUAD)." (PMID 38154103, 2023). "We then interrogated the expression of HOXC10 in the RNA-SEQ data set of the TCGA Lung Adenocarcinoma cohort." (PMID 32687064, 2020).